XPO4 (exportin 4)
Description:
Mediates the nuclear export of proteins (cargos), such as EIF5A, SMAD3 and isoform M2 of PKM (PKM2). In the nucleus binds cooperatively to its cargo and to the GTPase Ran in its active GTP-bound form. Docking of this trimeric complex to the nuclear pore complex (NPC) is mediated through binding to nucleoporins. Upon transit of a nuclear export complex into the cytoplasm, disassembling of the complex and hydrolysis of Ran-GTP to Ran-GDP (induced by RANBP1 and RANGAP1, respectively) cause release of the cargo from the export receptor. XPO4 then return to the nuclear compartment and mediate another round of transport. The directionality of nuclear export is thought to be conferred by an asymmetric distribution of the GTP- and GDP-bound forms of Ran between the cytoplasm and nucleus. Catalyzes the nuclear export of hypusinated EIF5A; a small cytoplasmic protein that enters nucleus and accumulates within nucleolus if not exported back by XPO4. Specifically mediates nuclear export of isoform M2 of PKM (PKM2) following PKM2 deacetylation by SIRT6. Also mediates the nuclear import of SOX transcription factors SRY and SOX2 (By similarity).
Synonyms: Exp4; KIAA1721; FLJ13046
Tractability: PROTAC: ubiquitination databases record sites on it; its protein half-life has been measured.
Gene: Protein-coding gene on chromosome 13 (20,777,329 to 20,903,048, reverse strand). Ensembl gene ENSG00000132953.
Subcellular location: Cytoplasm; Nucleus
Subcellular location (Human Protein Atlas): Nucleoplasm; Cytosol
Gene Ontology:
Molecular function: nuclear export signal receptor activity; protein binding; small GTPase binding
Biological process: positive regulation of protein export from nucleus; protein export from nucleus; nuclear transport
Cellular component: cytoplasm; cytosol; nucleoplasm; nucleus; nuclear pore
Genetic constraint (gnomAD): Loss-of-function variants: 37 observed, 134.02 expected, observed/expected ratio (o/e) 0.28, 90% interval 0.21 to 0.36. The upper end of that interval is the gene's LOEUF score, 0.36, which puts it in group 1 of 6, group 1 being the genes least tolerant of losing a copy. Missense variants: 889 observed, 1,340.9 expected, observed/expected ratio (o/e) 0.66, 90% interval 0.63 to 0.7. Synonymous variants: 431 observed, 478.82 expected, observed/expected ratio (o/e) 0.9, 90% interval 0.83 to 0.98.
Homologues: Orthologues: dog XPO4 (99% identical), macaque XPO4 (99% identical), mouse Xpo4 (99% identical), guinea pig XPO4 (97% identical), rat Xpo4 (97% identical), tropical clawed frog xpo4 (94% identical), chimpanzee XPO4 (93% identical), pig XPO4 (90% identical), zebrafish xpo4 (87% identical), Caenorhabditis elegans Y69A2AR.16 (26% identical). Paralogues in human: RANBP17 (20% identical), XPO7 (19% identical).
Diseases named in the same sentence as XPO4 in open-access papers:
XPO4 is named in the same sentence as 22 diseases in open-access papers, as found by Europe PMC text mining. Sharing a sentence is not in itself a finding about the gene and the disease. The quoted sentences say what the papers report.
liver cancer (5 papers, 2013 to 2025). An epithelial or non-epithelial malignant neoplasm that arises from the liver. "Further research would be needed to explore the XPO4 methylation contribution to liver cancer development in patients with MAFLD." (PMID 38722973, 2024). "XPO4 has been identified as a tumor suppressor in liver cancer and breast cancer, and its role in the export of eIF5A is known to be critical to the tumor-suppressing effects." (PMID 36182935, 2022). "As an example, we checked the 5hmC levels of two tumor suppressors: LZTS1 in breast cancer and XPO4 in liver cancer." (PMID 25248841, 2014). "All the results above provide new insights into better understanding biological indicators, such as XPO4, TGFβ1, ANGPTL4 and elF5A2, in the prediction and evaluation of liver cancer, as well as signaling pathways in the control of liver cancer." (PMID 23251252, 2013).
hepatocellular carcinoma (3 papers, 2015 to 2024). A malignant tumor that arises from hepatocytes. "According to recent research, there is evidence of a rise in the DNA methylation level of the XPO4 promoter in peripheral blood mononuclear cells (PBMCs) when chronic hepatitis B progresses to cirrhosis and hepatocellular carcinoma (HCC)." (PMID 38722973, 2024).
fibrosis (2 papers, 2022 to 2024). the formation of excess fibrous connective tissue in an organ or tissue in a reparative or reactive process. "To evaluate whether DNA methylation is implicated, we analysed XPO4 promoter CpG island methylation in human liver from subjects with MAFLD-related fibrosis or healthy controls (n = 10, per group) using bisulphite pyrosequencing." (PMID 38722973, 2024). "The involvement of XPO4 CNV in NAFLD was replicated in another study of Caucasians with metabolic-NAFLD (MAFLD), and XPO4 CNV was associated with fibrosis." (PMID 36672614, 2022). "Therefore, we investigated if the XPO4 CNV does this via regulation of DNA methylation in a cohort of 75 patients with MAFLD related fibrosis." (PMID 38722973, 2024).
cervical carcinoma (1 paper, 2015). A carcinoma arising from either the exocervical squamous epithelium or the endocervical glandular epithelium. "PDCD6 gene expression was higher in cells sensitive to L-OHP, whileexpression of PDS5B, UBL3, MTIF3,XPO4, CASC8, and GTF3A was lower.UBL3 was identified as one of seven genes that predict relapse andsurvival in early-stage cervical carcinoma patients." (PMID 26678268, 2015).
Hearing impairment (1 paper, 2023). A decreased magnitude of the sensory perception of sound. "The features of airway collapse and hearing impairment are common among our family, and overlapping microdeletions, as previously reported, with loss of XPO4 and part of the DFNB1 locus fitting most likely with these phenotypes." (PMID 37239394, 2023).
liver cirrhosis (1 paper, 2014). "Two of these CNVs, located at 13q12.11 and 12q13.2 respectively, harbour the exportin 4 (XPO4) and phosphodiesterase 1B (PDE1B) genes which are already known to be involved in the etiology of liver cirrhosis and HCC." (PMID 24743702, 2014).
liver fibrosis (1 paper, 2024). "In conclusion, our results suggest that DNA hypermethylation is in part responsible for the previously reported downregulation of XPO4 expression during progressive liver fibrosis." (PMID 38722973, 2024). "This suggests that epigenetic silencing of XPO4 is one of the mechanisms modulating XPO4 expression during liver fibrosis." (PMID 38722973, 2024). "We identified aberrant hypermethylation of XPO4 during hepatic fibrosis in humans and mice and an inverse correlation between XPO4 promoter methylation and its mRNA expression." (PMID 38722973, 2024). "The process of DNA methylation plays a crucial role in the repression of XPO4 transcription in the context of liver fibrosis development." (PMID 38722973, 2024). "Here, we explored the role of DNA methylation as an XPO4 gene regulatory element during liver fibrosis." (PMID 38722973, 2024). "A role for exportin 4 (XPO4) in the pathogenesis of liver fibrosis was recently identified." (PMID 38722973, 2024). "We sought to determine changes in hepatic XPO4 promoter methylation levels during liver fibrosis." (PMID 38722973, 2024). "However, the roles of XPO4 DNA methylation in fibrotic diseases, specifically liver fibrosis, remains speculative." (PMID 38722973, 2024).
male infertility (1 paper, 2022). The inability of the male to effect fertilization of an ovum after a specified period of unprotected intercourse. "At the organismal level, lower XPO4 dosage led to male infertility and neurological defects in Xpo4+/− mice, and cells in testes and hippocampal neurons of the heterozygotes exhibited the same abnormalities as were observed in cultured XPO4 KO cells." (PMID 36182935, 2022). "Testis and brain are two organs with high abundance of circRNAs, and insufficient XPO4 levels are detrimental, as Xpo4 heterozygous mice display male infertility and neural phenotypes." (PMID 36182935, 2022). "XPO4 heterozygous mice demonstrated male infertility, and significantly increased levels of ciR-loops, R-loops, and DNA damage were observed in the testes." (PMID 36182935, 2022).
non-alcoholic steatohepatitis (1 paper, 2015). "A recent genome-wide copy number (CNV) scan identified a 13q12.11 duplication in the exportin-4 (XPO4) gene to be associated with non-alcoholic steatohepatitis (NASH)." (PMID 26293807, 2015).
steatosis (1 paper, 2015). Increased lipid within the cytoplasm of cells. "Taken together, our data suggest that XPO4 CNV duplication is associated with histological severity of NAFLD especially with that of NASH, but may not be a distinctive marker for the progression from simple steatosis to NASH." (PMID 26293807, 2015).
tumor (10 papers, 2011 to 2025). "elF5A2 is amplified in human tumors, is required for proliferation of XPO4-deficient tumor cells and promotes HCC in mice." (PMID 23251252, 2013). "The XPO4 gene is a tumour suppressor gene located on the long arm of chromosome 13." (PMID 26293807, 2015). "This trend may be due to the role of XPO4 as a tumor suppressor." (PMID 26293807, 2015). "These genes, such as RFC1, XPO4, THEGL, SLC19A3, TBC1D4, and KCNH5, may have specific functions in metastatic tumour cells." (PMID 34507604, 2021). "Additionally, assessment of tumor behavior in HCC cell lines with or without rescuing XPO4 may confirm the therapeutic role of XPO4 in HCC." (PMID 23251252, 2013).
cancer (3 papers, 2013 to 2025). A tumor composed of atypical neoplastic, often pleomorphic cells that invade other tissues. "Expression of elF5A2 in the cancerous liver tissue was positively correlated with expression of XPO4 (CC=0.478, P<0.001) in carcinoma liver tissue." (PMID 23251252, 2013). "Expression of ANGPTL4 in the cancerous liver tissue was positively correlated with expression of XPO4 (CC=0.506, P<0.001) in carcinoma liver tissue, expression of elF5A2 (CC=0.469, P<0.001) in carcinoma liver tissue and expression of elF5A2 (CC=0.245, P<0.001) in paracancerous liver tissue." (PMID 23251252, 2013). "We found that the majority of XPO were significantly upregulated in tumors, while XPO4 and XPO7 were downregulated in some cancer types." (PMID 39882192, 2025). "Kaplan-Meier analysis indicated that the expression of XPO4 in carcinoma tissue did not correlate with survival function in overexpression and underexpression (P=0.202)." (PMID 23251252, 2013).
XPO4 also shares sentences with these, for which no sentence is quoted: breast carcinoma (2 papers); cutaneous melanoma (1); developmental delay (1); hepatitis B infection (1); infection (1); Laryngomalacia (1); non-alcoholic fatty liver disease (1); osteosarcoma (1); sarcopenia (1); sensorineural hearing loss (1).